IL10 (interleukin 10)
Diseases named in the same sentence as IL10 in open-access papers (continued):
Sharing a sentence is not in itself a finding about the gene and the disease.
inflammation (continued). "The ADAR1 p150 isoform plays a role in alveolar macrophages (AMs) in the progression of lung inflammation through modulating the release of inflammatory mediators, specifically the chemokine MIP-1 and the anti-inflammatory cytokine IL-10." (PMID 37764262, 2023). "Current research shows that the combination of ellagic acid-hydroxyapatite combination is able to reduce the main proinflammatory cytokine of bone inflammation, TNF-α so that it can increase bone growth factors, BMP-4 and OPN, through IL-10." (PMID 36561943, 2022). "In this study, LF-N2 significantly inhibited IL-6, increased the levels of IL-4 and IL-10 in serum, and the gene expression of NOS in gastric tissue, thereby inhibiting gastric inflammation and injury." (PMID 35299759, 2022). "Our study showed that IL-10 treatment significantly decreased TNF-α infiltration and the expression of IL-1β, IL-6, IL-8, and TNF-α in Ang II-induced vascular inflammation." (PMID 35528508, 2022). "Improve lung inflammation by inhibiting the excessive recruitment of M1 and M2 under TGF-β1 to achieve a therapeutic effect, reducing the levels of MCP-1, TNF-α, IL-1β, IL-6, IL-10,IL-13, and OSM." (PMID 34489700, 2021). "IL-10 is capable of effectively reducing the secretion activity of mast cells and TH2 cells and exerts a definite effect on the reduction of airway inflammation." (PMID 33133221, 2020). "After the model of intestinal inflammation was induced, the addition of FDC reduced the secretion of IL-10, IL-4, and TNF-α, indicating that FDC can slightly relieve intestinal inflammation." (PMID 32765533, 2020). "Our results show that PO suppresses lung inflammation by the reduction of IL-β, IL-6, TNF-α, PGE2, and TGF-β, as well as by the increase of IL-10 levels." (PMID 30609661, 2019). "In an allergic airway disease model, deletion of IRF4 expression in CD11c+ cells attenuated Th2-type lung inflammation, and IRF4 was found to directly modulate IL-10 and IL-33 production by DCs, promoting Th2 differentiation and inflammation." (PMID 29343807, 2018). "In ALI models, IL-10, prostaglandin E2, and KGF were shown to be secreted by MSCs to inhibit lung inflammation or protect against alveolar epithelium injury." (PMID 30050579, 2018). "IL-10 is of particular therapeutic interest in IBD, since it has been shown that IL-10−/− mice spontaneously develop intestinal inflammation characterized by discontinuous transmural lesions." (PMID 30069221, 2018). "The intestinal inflammation is characterized by a Th1 and Th17-mediated responses with enhanced expression of TNF-α, IFN-γ, IL-1β, IL-12, IL-6, IL-10 and IL-1761." (PMID 29872077, 2018). "When 1,3-β-glucan-induced lung inflammation developed into the late stage, anti-CD22 treatment significantly limited the increase of IL-10 compared with that in glucan group." (PMID 28428789, 2017). "Chronic inflammation is known to play a major role in the pathological mechanism of COPD, and inflammatory cytokines, such as MCP-1, IL-2, IL-6, and IL-10, are known to promote inflammation." (PMID 29234369, 2017). "Intestinal inflammation in colitic controls was characterized by a marked increase in pro- and anti-inflammatory cytokines TNF-α, IFN-γ, IL-1β, IL-6, IL-12, and IL-10, compared to normal controls." (PMID 27293323, 2016). "By adoptive transfer of AvCystatin-primed peritoneal exudate cells we were able to induce IL-10 producing CD4 T cells and ameliorate airway inflammation." (PMID 27560829, 2016). "It is known that both IL-10 and TGF-β have an important role in the establishment of tolerance and suppression of inflammation diseases." (PMID 26565726, 2015). "A variety of cytokines, including IL-6, IL-8, IL-10 and ICAM-1, are considered to participate in lung inflammation, which is closely related to the development of BPD." (PMID 23935746, 2013). "Thus, IL-10 gene delivery could be more effective in the treatment of local airway inflammation." (PMID 16677403, 2006).
inflammation (continued). "In experimental models of antigen- induced arthritis, IL-10 has shown protective effects, and mice lacking IL-10 exhibit exacerbated joint inflammation." (PMID 41009491, 2025). "Several reports suggest that IL-10 can inhibit antigen presentation and downregulate the formation and secretion of IL-1, IL-6, TNF-α, and other critical inflammatory aspects in macrophages and T cells, thus improving IBD intestinal inflammation." (PMID 38891089, 2024). "IL10 is an anti-inflammatory cytokine and mice lacking the gene develop spontaneous intestinal inflammation in the presence of microbiota." (PMID 36572998, 2023). "have revealed that HDAC11 could inhibit IL-10 expression and induce inflammatory antigen-presenting cells, showing agreement with the positive correlation between HDAC11 and mild chronic inflammation in some degree." (PMID 36324577, 2022). "Moreover, we also exhibited that the PO extract (100 and 200 mg/kg, p.o.)inhibited lung inflammation by downregulating TNF-α, IL-6, IL-β, TGF-β, and PGE2 levels and upregulating the expression level of IL-10." (PMID 34381307, 2021). "Some authors suggest a new subset of Th17 producing IL-10 cells that do not induce tissue inflammation and they contribute, actually, to inhibit autoimmune inflammation." (PMID 30233389, 2018). "High concentrations of IL-1RA, IL-8, IL-10, and IP-10 correlate with active inflammation in PSS, while FU may trigger chronic inflammation." (PMID 29944680, 2018). "In WT mice, intranasal OVA challenge does not results in lung inflammation while in IL-10 KO or IL-10/IL-12-KO mice intranasal OVA challenge induces airway neutrophilic inflammation and lung inflammation associated with IFNγ or IL-17 production." (PMID 28220116, 2017). "In addition, these mφ seem to facilitate secondary expansion and maintenance of antigen-specific Foxp3+ Treg cells through IL-10 production and consequently, to regulate TNBS-induced intestinal inflammation." (PMID 27576902, 2016). "In the present study, we demonstrate that TCDD-induced AhR activation reduced non-eosinophilic airway inflammation via the inhibition of Th17 differentiation and IL-17 expression and the promotion of Treg differentiation and IL-10 production." (PMID 26938767, 2016). "IL-10 is a potent anti-inflammatory cytokine that suppresses the secretion of proinflammatory cytokines, allergen-induced airway inflammation, and non-specific airway responsiveness." (PMID 25157974, 2014). "Our study provides clear evidence that irrespective of the cause of liver damage, Foxp3 expression, and not IL-10 and TGF-β1, appeared with a dramatic increase that relates to the intensity of liver inflammation." (PMID 21772667, 2011). "With regard to OVA-induced airway inflammation, we demonstrated that the magnitude of immune response with respect to goblet cell hyperplasia, airway reactivity, BAL fluid IL-5, IL-10 and serum OVA-specific IgE production is significantly lower in C57BL/6 mice than in BALB/c." (PMID 19438585, 2009). "Our results showed that in vivo delivery of IL-10 or IL-12 gene alone could efficiently inhibit AHR and airway eosinophilic inflammation." (PMID 16677403, 2006). "OVA-Mφ produced higher levels of IL-10 upon stimulation with ISS-ODN compared to stimulation with LPS, suggesting a correlation between the levels of IL-10 produced by the Mφ and the extent of suppression of allergen-induced airway inflammation." (PMID 15538945, 2004). "In addition, we constructed an immune inflammation-related PPIN (confidence level >0.4) involving interleukin-4 and interleukin-13 signaling, interleukin-10 signaling, and arachidonic acid metabolism, and calculated the degree, betweenness and closeness of each node in the network." (PMID 36003498, 2022).
inflammation (continued). "Cryotherapy did not decrease IL-10 levels in the present study, suggesting its action against progression of acute joint inflammation and demonstrating that IL-10 is beneficial as anti-inflammatory cytokine; however, the action pathway of IL-10 needs to be better investigated." (PMID 35061737, 2022). "Systemic inflammation in obese boys was characterized by higher expression of TNF-β (p = 0.011), IL-15 (p = 0.004), and IL-2 (p = 0.046) and significantly lower concentrations of anti-inflammatory cytokines such as IL-10 (p = 0.035) and IL-13 (p = 0.002), compared to eutrophic males." (PMID 33526854, 2021). "Additionally, Exo-d-MAPPS promoted the expansion of immunosuppressive IL-10-producing alternatively activated macrophages, regulatory DCs, and CD4+FoxP3+T regulatory cells in inflamed lungs which resulted in the attenuation of chronic airway inflammation." (PMID 32257769, 2020). "Thus, increased efferocytosis by alveolar macrophages following isoflurane treatment may trigger an anti-inflammatory response and resolution of lung inflammation through the induction of TGF-β1 and IL-10." (PMID 28671983, 2017). "In patients with low level CHB without evidence of liver inflammation, IL-10 was not elevated and its blockade alone could not rescue NK function, which instead required additional TGF-β blockade." (PMID 21187913, 2010). "Moreover, in HIV negative men with chronic inflammation of the prostate, elevated levels of IL-10 and inflammatory cytokines are found in the seminal plasma, indicating protein production." (PMID 18347738, 2008). "In this context, epistatic interactions between MMP1, IL10, and IL17A are biologically plausible, as excessive extracellular matrix degradation, impaired anti-inflammatory regulation, and enhanced Th17-driven responses may act synergistically to promote chronic periapical inflammation." (PMID 41614937, 2026). "Besides, the correlations between BIRC3 expression and asthmatic eosinophilic/allergic inflammation indicators (FeNO, IgE, and EOS%), pulmonary function (FEV1, FEV1% pred, FVC% pred, and FEV1/FVC), and inflammatory cytokines (IL-4, IL-5, IL-13, IL-25, IL-10, IL-33, and TSLP) were analyzed." (PMID 35287655, 2022). "Interestingly, in cases of mild pulmonary inflammation (e.g., low-dose LPS), pulmonary macrophages exhibit low c-MAF expression, and IL-10 is not induced under these conditions." (PMID 41312367, 2025). "On the contrary, in an infectious model of acute gut inflammation, the authors have shown that the therapeutic effects of both PAMAM and optimized polypropyletherimine (PETIM) dendrimers do not rely on an enhancement of the expression of IL10." (PMID 29799517, 2018). "Importantly, IL-10-/-Mφ that were loaded with OVA and stimulated with ISS-ODN ex vivo, failed to suppress OVA-induced airway inflammation." (PMID 15538945, 2004). "Four out of nine DKO mice under conventional housing developed large bowel inflammation and five out of 19 DKO mice kept under SPF conditions, whereas only two out of 10 IL‐10−/− mice under conventional housing developed inflammation and none of the IL‐10−/− mice kept under SPF conditions." (PMID 32350866, 2020). "However, ELISA tests for detection of IL-10 showed that IL-10 production in the lungs was similar between the YFTL-treated and untreated mice at three days p.i., indicating that IL-10 is not involved in the YFTL-mediated inhibition of early lung inflammation." (PMID 30204794, 2018). "Thus, the lack of efficacy of cis-UCA in the IL-10−/− mouse suggests the possibility that IL-10 secreting T-regulatory cells or γδ+ T cells may be critical for cis-UCA effects, and further, that the increased levels of IFNγ are not the primary driver of gut inflammation in this model." (PMID 21060867, 2010).
bacterial infection (255 papers, 2006 to 2026). "After obtaining nearly all of the results, we found that the variable “any bacterial infection” was statistically associated with IL-1β (p-value < 0.05), IL-6 (p-value < 0.05), IL-8 (p-value < 0.05), IL-10 (p-value < 0.05), and TNF-a (p-value < 0.05)." (PMID 40732663, 2025). "From these, three HTL epitopes were selected based on their conservation across alleles, and ability to induce IL-4 and/or IL-10 cytokines, which are critical in bacterial infections." (PMID 40863232, 2025). "In the case of intracellular bacterial infections, the IL-10 overexpression is associated with the host’s immune suppression and bacterial persistence." (PMID 39064007, 2024). "sIgA plays a crucial role in preventing pathogenic bacterial infections by aggregating in the mucin layer, binding to mucin, and also promoting the anti-inflammatory cytokine IL-10, which influences the maturation of dendritic cells." (PMID 38898418, 2024). "IL-10 is an anti-inflammatory cytokine that promotes innate immune responses from tissue epithelia, helping to limit damage caused by both viral and bacterial infections." (PMID 39336593, 2024). "Despite this association with the chronicity of EP and its synergistic effect with other pathogens in cases of the PRDC, IL-10 has been also linked to clinical protection and lung lesion reduction in bacterial infections." (PMID 38731294, 2024). "IL-10 is an anti-inflammatory cytokine that has been associated with innate immune suppression during bacterial infections including GBS (30, –, 32)." (PMID 37747229, 2023). "The immune response in malnourished children has been shown to be geared towards Th2 activation, resulting in the proliferation of anti-inflammatory cytokines, such as IL-4 and IL-10, which can increase the predisposition to protozoa and bacterial infections." (PMID 37111135, 2023). "For example, IL-10 expression is known to be induced following pathogenic bacterial infection, as well as lipopolysaccharide (LPS) induction." (PMID 37513733, 2023). "Nonetheless, limited research delves into the diagnostic utility of IL-6 and IL-10 in adult patients with bacterial infections." (PMID 37986183, 2023). "Forty-three biomarkers were investigated, of which 6 (CRP, PCT, IL-8, IL-6, IL-10, and TNFα) were significantly associated with bacterial infection at admission, studied in multiple studies, and provided predictive data." (PMID 35372147, 2022). "Protozoan, viral and bacterial infections in IL-10-deficient mice also show potent increases in Th1 and Th17 cytokines, associated with rapid pathogen clearance but also with acute and often fatal immunopathology." (PMID 35428872, 2022). "The augmented IFN and IL-10 expression incapacitated antibacterial immunity of myeloid cells and caused failure to control bacterial infection in severe liver fibrosis and cirrhosis." (PMID 36052075, 2022). "This polarized response can alter the equilibrium between IL-17 and IL-10 secretion, and increases susceptibility to subsequent bacterial infection." (PMID 32997525, 2021). "Bregs have immunosuppressive properties, they mainly produce IL-10 contributing to the anti-inflammatory activity and their expansion have been associated with the persistence of bacterial infections." (PMID 33584691, 2020). "Opn was shown to have an impact on type-1 immunity to bacterial infections as OPN deficient mice have increased Il-10 production." (PMID 32038649, 2019). "The studies performed so far that evaluate the role of IL-10 during bacterial infections have been performed using antibiotic susceptible bacteria." (PMID 30279680, 2018). "The pretreatment of blood immune cells with EPs 7630 lowered their secretion of TNF-α and IL-10 and caused an IL-6 dominant response during second stimulation with viral or bacterial infection-mimicking agents." (PMID 26406906, 2015).
bacterial infection (continued). "Previous research suggests that the secretion of IL-10 due to IAV infection predisposes mice to secondary bacterial infection due to the inhibitory effects of this cytokine." (PMID 23074662, 2011). "Although IL-10−/− mice are susceptible to bacterial infection/colonization, it is important to underline the selective nature of their host responses to various bacterial strains." (PMID 19841748, 2009). "Furthermore, IL6 and IL10, are recognized as an early and sensitive indicator of bacterial infections, with substantial evidence supporting its diagnostic utility in severe CAP." (PMID 41018059, 2025). "It has previously been established that IL-10 may play a role in the clearance of bacterial infections caused by K. pneumoniae." (PMID 40943371, 2025). "IL-2, IL-6, and IL-17 are systemic pro-inflammatory cytokines, and IL-10 is an anti-inflammatory cytokine, the concentration of which increases in acute inflammatory processes and exacerbations of chronic diseases caused by a viral or bacterial infection." (PMID 39937802, 2025). "Conversely, IL-10 overexpression may induce a temporary immune system suppression, which increases the susceptibility of the host to bacterial infections." (PMID 34732259, 2021). "Hence, the impairment of these processes likely accounts for the ability of NK cell IL-10 to increase susceptibility during Lm, and possibly other, bacterial infections." (PMID 27295349, 2016). "To study the impact of bacterial infection on host immunological responses, we monitored mRNA levels of genes encoding inflammation markers TNFα, IL-1β, IL-22 and IL-10, including pro- and anti-inflammatory cytokines, in axenic and infected zebrafish larvae at 1, 2 and 3 dpi." (PMID 22911651, 2012). "Enhanced production of IL-10 may increase the susceptibilityof DEP-exposed lung to bacterial infection." (PMID 16882535, 2006). "It was also demonstrated that DEPe suppressed Listeria monocytogenes-induced secretion of IL-12 and TNFα in rat alveolar MΦ and that DEP-enhanced production of IL-10 may also increase the susceptibility of diesel particulate matter-exposed MΦ to bacterial infection." (PMID 25710172, 2015). "Pro-inflammatory cytokines, such as IL-1β and IL-6, can trigger inflammatory responses, while anti-inflammatory cytokines, like IL-10, support the host immune system in defending against bacterial infections." (PMID 40403037, 2025). "Cytokines such as TNF-α, IL-6, and IL-10, released during viral or bacterial infections, bind to specific receptors on C-fiber neurons of the vagus nerve, causing depolarization and increased excitability." (PMID 41044788, 2025). "An exaggerated IL-10 response during severe bacterial infections can compromise the protective anti-inflammatory pathways necessary for effective pathogen clearance, thereby promoting immune dysregulation and worsening clinical outcomes." (PMID 41018059, 2025). "Bifidobacterium longum and Lactobacillus rhamnosus promote the production of anti-inflammatory cytokines such as interleukin-10 (IL-10), which mitigates systemic inflammation and enhances the host’s resistance to viral and bacterial infections." (PMID 39857684, 2025). "Other markers were also examined, such as IL-10, IL-17A, and M-CSF, which regulates the mobilization of neutrophils and macrophages/monocytes against bacterial infection." (PMID 39199203, 2024). "Overexpression of IL-10 worsens the outcome of bacterial infections, including S. aureus infections." (PMID 39178306, 2024). "Upregulation of GJB2, VNN1, DUSP4, SerpinB7, and IL10, and downregulation of PKMYT1, S100A4, GGTA1P, and SLC22A31 were most strongly associated with bacterial infection." (PMID 39395995, 2024). "Previous studies found that an increased expression of il-10 in crucian carp (Carassius auratus) and grass carp (Ctenopharyngodon idella) improved the immune ability of fish to resist bacterial infection." (PMID 39061564, 2024).